AURKA (aurora kinase A)
Diseases named in the same sentence as AURKA in open-access papers (continued):
Sharing a sentence is not in itself a finding about the gene and the disease.
tumor (continued). "Additionally, AURKA expression exhibited associations with bile acid metabolism, a factor often considered pro-carcinogenic in EAC due to its potential to induce DNA damage and influence the tumor microenvironment." (PMID 37965456, 2023). "Notably, AURKA expression was notably low in LAML tumor tissues (p<0.001)." (PMID 37965456, 2023). "Moreover, AURKA is expressed significantly higher in most tumor tissues relative to normal tissues." (PMID 35217647, 2022). "The results showed that knockdown of SIN1 could attenuate the promotion of tumour growth by AURKA." (PMID 36471438, 2022). "Furthermore, it was shown that INI1/SNF5, core component of the mammalian SWI/SNF complex, repressed AURKA transcription in rhabdoid but not in non-rhabdoid tumour cells, as it associated with AURKA promoter only in the former case." (PMID 36067794, 2022). "Therefore, AURKA leads to tumor growth and proliferation through the mentioned pathways." (PMID 36678556, 2022). "Additionally, circPVT1 represses the function of the miR-497-5p as a tumor suppressor, consequently leading to an increase in the expression of genes that regulate cell proliferation, such as aurora kinase A (AURKA) and BUB1 mitotic checkpoint serine/threonine kinase (BUB1)." (PMID 33803232, 2021). "Interestingly, AURKA is involved in tumor metastasis after radiotherapy for HCC." (PMID 34257537, 2021). "Notably, AURKA expression is reduced in tumor tissues versus normal tissues in the THCA dataset." (PMID 33451333, 2021). "In addition, combination of PHA-739358 with sorafenib resulted in an additive effect on tumor growth inhibition, thus highlighting that inhibition of AURKA, either alone, or in combination with sorafenib, may be a promising therapeutic approach for HCC." (PMID 32018226, 2020). "Furthermore, the size of tumour xenografts decreased upon AURKA knockdown." (PMID 32429269, 2020). "Moreover, AURKA may have a role in tumor cell growth and migration, through its interaction with the liver kinase B1 (LKB1)." (PMID 31383005, 2019). "Tumor cell migration stimulated by LMW-HA is often associated with an epithelial-mesenchymal transition mediated by CD44 through activating PI3K/AKT and TGFβ signaling, while RHAMM is linked to increasing tumor cell migration via regulating ERK and AURKA/beta-catenin pathways." (PMID 31134064, 2019). "In addition to the multivariate analyses using standard clinical and pathological tumor characteristics, we evaluated if AURKA as marker of proliferation might add prognostic information." (PMID 31231679, 2019). "Thus, the presence of multiple clones within a tumor might also mask the effect of AURKA gain present in a minority of the clones in the tumor." (PMID 29760449, 2018). "However, to determine whether bexarotene could affect tumor growth in VHL-deficient cells by modulating AURKA, we established an RCC tumor xenograft using 786-0 (VHL-deficient) cells in athymic nude mice (Foxn1nu)." (PMID 30518623, 2018). "In order to evaluate the biologic effects of high-level AURKA expression, we transduced the UC7 and UC11 cells with an AURKA-specific shRNA construct or a non-targeting control and characterized the effects on proliferation and other biological properties associated with tumor progression." (PMID 28102366, 2017). "Moreover, AURKA overexpression promotes cell proliferation and tumor progression and metastasis." (PMID 28152093, 2017).
tumor (continued). "AURKA may mediate chromosomal instability in tumor cells by regulating error-prone NHEJ DNA repair." (PMID 28881569, 2017). "Alisertib is an investigational, selective, small-molecule inhibitor of Aurora kinase A. As demonstrated with other Aurora kinase A inhibitors, alisertib has been shown to induce cell cycle arrest, polyploidy and cell death by mitotic catastrophe in a subset of tumor cell lines." (PMID 27385211, 2016). "We therefore investigated whether AURKA could revive dormant tumor cells to promote metastasis." (PMID 27356739, 2016). "Thus, AURKA has been used as a potential target for the development of tumor-targeted therapeutics." (PMID 26468983, 2015). "However, we did not identify a significant level of endoreduplication downstream of AKI except at relatively high doses in vitro and within our treated tumours in vivo, which may reflect concomitant inhibition of AURKA and AURKB at these dosages." (PMID 23328114, 2013). "Moreover, our study is the first to demonstrate an association between high AURKA-CN and improved clinical outcome among patients with mCRC receiving chemotherapy, with a more pronounced association noted among patients with KRAS wild-type tumours." (PMID 22240781, 2012). "The interactions between siR-NAs targeting AURKA and Kinesin-5i suggest that combination therapy with these compounds might be more effective than therapy with either compound alone, and could help to overcome tumor resistance to either single therapy." (PMID 19259408, 2008). "Other tumor-suppressive miRNAs, including miR-15a, f, and miR-34a, target BCL2 and AURKA to promote apoptosis and inhibit proliferation, while oncogenic miRNAs (oncomiRs) like miR-21 and miR-221/222 drive drug resistance by targeting PTEN and other pathways." (PMID 41596492, 2026). "Genetic or pharmacological inhibition of AURKA restored NCOA4-mediated ferritinophagy, synergized with ferroptosis inducers (sorafenib or IKE), and potently suppressed tumor growth both in vitro and in vivo." (PMID 42026022, 2026). "AURKA, ranked second, was upregulated in PTEN mutant LGG, PRAD, SARC, and SKCM tumours (P-value = 1.04e − 69)." (PMID 40775769, 2025). "The ZNF468 overexpression group exhibited the highest tumour volume and weight, followed by the ZNF468 overexpression combined with AURKA knockdown group, and the control group had the smallest tumours." (PMID 40702875, 2025). "The expression levels of pivotal regulatory genes (CDCA8, AURKA, and PLK1) were significantly higher in tumor samples than in control samples, whereas NR3C2 was significantly downregulated in cancerous tissues." (PMID 41357242, 2025). "Gene expression analysis of the GSE42977 dataset revealed significant upregulation of AURKA, CDK2, and VPS37A in MPM tumor tissues compared to normal mesothelial and lung tissues." (PMID 40180891, 2025). "The combination of AURKA inhibitor and PD-L1 further expanded intratumoral CD8+ effector and CD4+ memory T-cell infiltrates, amplifying anti-tumor immunity." (PMID 41415276, 2025). "To verify whether monocyte- and macrophage-CM modulate the tumor plasticity of SCC cells, we analyzed the expression of genes associated with epithelial-mesenchymal transition (EPCAM, SOX2), stemness (NANOG, MYC, EZH2), and neuroendocrine differentiation (CHGA, AURKA, MYCN)." (PMID 41259557, 2025). "Alisertib is a highly potent and selective AURKA inhibitor (IC50 = 1.2 nM), demonstrating strong anti-tumor activity in preclinical studies and promising clinical efficacy." (PMID 40949156, 2025). "The seven genes comprising the HMR model (SUZ12, KAT2A, AURKA, BUB1, SUV39H2, UTY, and PCGF5) are critically involved in epigenetic modification, tumor progression, supporting their prognostic value in MM." (PMID 40949882, 2025).
tumor (continued). "The causal relationship between NKX6.3 depletion, cell cycle dysregulation, and the subsequent amplification of AurkA and TPX2 underscores the complex molecular pathways involved in CIN and tumor progression." (PMID 39833908, 2025). "In biological experiments, AURKA, BID, and PLA2G6 functioned as tumor promoters by enhancing the proliferation and migration of ccRCC cells." (PMID 40271062, 2025). "Targeting Aurora Kinase A along with CDK2 inhibition should destabilize spindle dynamics, increasing mitotic errors and eliminating polyploid tumor cells." (PMID 40232858, 2025). "Our findings revealed that EZH2, AURKA, BID, PLA2G6, and EPAS1 exhibited significantly elevated expression levels in ccRCC tumor tissues compared to normal tissues." (PMID 40271062, 2025). "FBXW7 has also been shown to negatively regulate AURKA, further supporting the value in future experiments exploring targeting of AURKA in FBXW7 mutant cell lines and tumours." (PMID 40775769, 2025). "In addition, AURKA may also enhance tumor escape by modulating the tumor immune microenvironment." (PMID 40718709, 2025). "The discovery that CDK1, TOP2A, AURKA, TPX2, BUB1B, and CENPF are key cell-cycle regulators in NSCLC emphasizes the ongoing contribution of mitotic dysregulation to tumor growth." (PMID 41080754, 2025). "The PI3K/AKT activity exhibited marked upregulation in tumour tissues of the ZNF468 overexpression group, and this activation was markedly reduced following AURKA knockdown." (PMID 40702875, 2025). "Tumor tissues exhibited significant upregulation of CDCA8, AURKA, and PLK1, whereas NR3C2 was notably downregulated (p < 0.0001)." (PMID 41357242, 2025). "This mirrors findings for AURKA, a close homolog of AURKB, which has been reported to facilitate tumor progression via modulation of alternative splicing." (PMID 40784984, 2025). "AURKA (Aurora kinase A) is overexpressed in HCC, promoting tumor proliferation, metastasis, and invasion." (PMID 41226349, 2025). "In particular, Aurora kinase A (AURKA) expression is 7.9-fold higher in human and murine MPNST samples than in healthy, and its pharmacological inhibition reduces tumor cell survival in vitro and in vivo." (PMID 41463204, 2025). "In this context, the combination of inhibitors of AURKA and EGFR has been explored and shown promising activity in several tumor types." (PMID 38639476, 2024). "Preclinical studies have demonstrated that BRG1 inactivation increases tumor invasiveness and enhances sensitivity to targeted agents inhibiting oxidative phosphorylation and drugs targeting EZH2, AURKA, ATR, CDK4, and CDK6." (PMID 39465834, 2024). "Several AURKA inhibitors, including alisertib (MLN8237), danusertib, and ENMD-2076, have undergone clinical trials and shown certain antitumor effects in multiple tumor types." (PMID 38521813, 2024). "The analysis of showed that PHF19, AURKA, CHAF1B and AURKB were up-regulated in the tumor group, NAP1L2, TONSL, SATB2 and HDAC9 were down-regulated in the tumor group." (PMID 38212708, 2024). "The role of Asp132-cleavage of AURKA induced by the chemotherapy drug paclitaxel was investigated using TUNEL, immunohistochemistry assay in mouse tumor xenograft model and patient tissues." (PMID 38994036, 2024). "In this study, two genes (AURKA and S1PR1) were screened as hub genes of OSU-2S treatment NSCLC by survival analysis and expression analysis, and the study has confirmed the tumour-growth-suppressive effect of OSU-2S in in vivo and in vitro experiments." (PMID 38794152, 2024). "Other studies have described that UBE2C, along with the other signaling molecules such as AURKA, EMT, GRIK3, CDK1, and claudin 19, activates the WNT/β-catenin signaling pathway, thus altering tumor biology." (PMID 39479352, 2024).
tumor (continued). "In this study, we identified AURKA inhibitors, including MLN8237, which are undergoing clinical trials in various tumor types, including NSCLC, as potential targeted drugs for KEAP1 mutant NSCLC." (PMID 38521813, 2024). "An additional link between the deregulation of the AurkA/TPX2 complex and chromosomal instability in tumours comes from studies on the phosphatase PP6, which has been demonstrated to be the AurkA T-loop phosphatase when the kinase is complexed with TPX2." (PMID 39195284, 2024). "Aurora kinase A (AURKA) and tumor-infiltrating lymphocytes (TILs) are both known to play an essential role in tumorigenesis." (PMID 38903715, 2024). "A recent study has demonstrated that the overexpression of AURKA, CDK1, and PLK1 is positively correlated with tumor grades and stage." (PMID 38672246, 2024). "Among them, PHF19, AURKA, CHAF1B and AURKB were up-regulated in the tumor group, NAP1L2, TONSL, SATB2 and HDAC9 were down-regulated in the tumor group." (PMID 38212708, 2024). "In conclusion, these findings highlight AURKA as a promising target for GBM therapy, especially in combination treatments aimed at modulating immune responses and creating an unfavorable tumor environment." (PMID 38995006, 2024). "Correlation analysis revealed a significant correlation of AURKA, AURKB, BUB1, HJURP, TOP2A, and TTK with tumor proliferation, G2M checkpoint, MYC targets, and DNA replication." (PMID 38726001, 2024). "For instance, tumor-suppressor miRNAs such as and miR-199b-3p, miR-129-3p, miR-490-3p, and miR-26a-5p directly repress AURKA, whereas lncRNAs like MALAT1 and TUG1 indirectly upregulate AURKA by sponging and downregulating tumor-suppressor miRNAs." (PMID 39598228, 2024). "We assessed AURKA expression and TIL infiltration in MTC tumor tissues using IHC staining and HE staining." (PMID 38903715, 2024). "Bioinformatic analysis of the data obtained from qRT-PCR and the subsequent WB analysis shows that ASncmtRNA KD induces a differential regulation of both AURKA and TOPO2A between the tumor cell lines MDA-MB-231/MCF7 and control cells HMEC." (PMID 39000605, 2024). "By the same criteria, the onco-signaling genes AURKA, KRAS, and MYC were up-regulated in over 90%, 60%, and 50% of all tumor types, respectively." (PMID 38649187, 2024). "Treatment of NB cells with alisertib, a specific AURKA inhibitor, inhibited cell growth, degraded MYC protein levels, and resulted in inhibition of tumor growth in a xenograft mouse model." (PMID 39585848, 2024). "Through AURKA-mediated phosphorylation of LDHB, glycolysis and biosynthesis were effectively promoted, thereby promoting tumor progression." (PMID 37333985, 2023). "AURKA forms a complex with N-MYC, protecting it from FBW7-mediated degradation, and inhibitors of AURKA disrupt the MYC–AURKA complex, promoting N-MYC degradation and tumor regression." (PMID 37755397, 2023). "We observed amplifications in chromosome arm 20q (chr20q) in 74/373 tumours (19.8%), which includes SRC, TOP1, BCL2L1, ZNF217, AURKA, GNAS and ARFRP1." (PMID 37666855, 2023). "AURKA as the stemness-related genes and its upstream transcription factor NCAPG were proven to have a higher expression level in tumor samples than normal sample in the Oncomine database." (PMID 36703644, 2023). "NK1R (Tachykinin Receptor 1) activates the AURKA/MYCN signaling pathway through PKCα and its knockdown results in the reduction of tumor burden and suppression of NE features in vivo." (PMID 37761978, 2023). "Our findings revealed significant correlations between AURKA, CDKN1A, and STEAP3 and tumor exclusion." (PMID 37608887, 2023). "In addition, the AURKA inhibitor could rescue ciliogenesis and reverse the acquiring resistance to sonidegib (SMO inhibitor) of tumor cells due to PC deficiency, revealing the essential role of AURKA on tumor cell PC formation." (PMID 37101292, 2023).
tumor (continued). "Targeting of AURKA successfully abolished CXCR7-driven PCa cell proliferation in vitro and xenograft tumor growth in vivo." (PMID 37347559, 2023). "In the current work, we identify AURKA as a major mediator of CXCR7-driven PCa and show that AURKA inhibition reduces tumor growth." (PMID 37347559, 2023). "Studies have shown that AURKA is an important tumor regulator, which is upregulated in OSCC cell lines and tumor specimens from patients." (PMID 37765514, 2023). "AURKA and TOP2A were downregulated in both tumor cell lines but were, conversely, strongly upregulated in HMECs." (PMID 37888205, 2023). "Using the Gene Expression Profiling Interactive Analysis (GEPIA) website, we compared the mRNA levels of AURKA in normal and GBM tumor tissues." (PMID 36816802, 2023). "The results revealed that AURKA, BIRC5, CCNB1, CDK1, CDKN3 and TYMS were significantly upregulated in tumor tissues." (PMID 37393234, 2023). "In addition, we found that the expressions of AURKA, CCNA2, CCNE1, CDK1, CHEK1, and PLK1 were all positively correlated with TMB, which was consistent with previous research results, and there was a positive correlation between tumor dryness and tumor mutation burden." (PMID 36483630, 2022). "AURKA and AURKB play key roles in mitosis, and some natual products targeting AURKA and AURKB exert anti-tumor effects in vitro." (PMID 35699421, 2022). "These include three members of the Aurora kinase family (AURKA, AURKB, and AURKC), serin/thereonine kinases that regulate multiple aspects of tumor growth and progression." (PMID 36482411, 2022). "For mouse subcutaneous tumours, P-AKT was also significantly downregulated in the AURKA low-expressing group compared to the control." (PMID 36471438, 2022). "To further identify the hub genes in the high- and low-AURKA groups, we performed WGCNA co-expression network analysis on GSE12452 and GSE13598 tumor samples, respectively." (PMID 36072667, 2022). "In turn, AURKA links the interaction between hnRNP K and YTHDC1, thereby enhancing the production of tumor-promoting isoform RBM4-S." (PMID 35361747, 2022). "For mouse subcutaneous tumours, SIN1 was also downregulated in the AURKA low-expressing group compared to the control." (PMID 36471438, 2022). "This signaling pathway reduces cell death by altering the expression of genes involved in the apoptotic process such as BIM, NFκB1, NFκB2, AURKA, and AURKB, thereby increasing tumor growth." (PMID 36482411, 2022). "Consistent with the RT-qPCR results, Western blot also showed that the protein levels of P4HA1, MLLT11, AURKA, and GOT1 were markedly higher in the tumor tissues than those in the paratumor tissues." (PMID 35558559, 2022). "Compared with adjacent normal tissues, the relative protein levels of AURKA and RBM4-S were evidently increased in tumor tissues, while the relative protein levels of RBM4-FL were evidently decreased in tumor tissues." (PMID 35361747, 2022). "Together, these data demonstrate that small-molecule AURKA nuclear translocation inhibitors JNJ and PHA suppress RBM4 splicing towards RBM4-S, thereby restraining tumor growth." (PMID 35361747, 2022). "RT-qPCR results showed that the abundance of P4HA1, MLLT11, AURKA, and GOT1 were significantly elevated in tumor tissues." (PMID 35558559, 2022). "To further identify the hub genes in the high and low AURKA groups, we performed WGCNA co-expression network analysis on GSE12452 and GSE13598 tumor samples." (PMID 36072667, 2022).